IL10 (interleukin 10)
Diseases named in the same sentence as IL10 in open-access papers (continued):
Sharing a sentence is not in itself a finding about the gene and the disease.
Chronic colitis (126 papers, 2007 to 2025). A chronic inflammatory disease of the large intestine (colon, cecum and rectum). "Daily treatment with DHA at 35.5 mg/kg for two weeks can ameliorate changes to intestinal permeability in IL-10-deficient mice with spontaneous chronic colitis by increasing the expression of TJ-associated proteins, occludin, and ZO-1." (PMID 38672464, 2024). "Here, we examined the role of α4β7 integrin during chronic colitis using IL-10−/− mice, β7-deficient IL-10−/−, IgA-deficient IL-10−/− mice, and antibody blockade of MAdCAM-1." (PMID 34433904, 2022). "Mutation or functional loss of IL-10 leads to UC severity and IL-10 KO induces spontaneous chronic colitis." (PMID 35620404, 2022). "Chronic colitis in IL-10 KO mice was associated with a half-fold decrease in TH levels versus the wild-type littermates." (PMID 34884737, 2021). "This prompted us to apply a murine chronic colitis model by using aged conventional interleukin (IL)-10 deficient (IL-10-/-) mice." (PMID 32664563, 2020). "Enterococcus faecalis is a resident member of the human intestinal core microbiota that has been linked to the pathogenesis of IBD and induces chronic colitis in susceptible monoassociated IL-10-deficient (IL-10−/−) mice." (PMID 31281321, 2019). "Mice deficient for the anti-inflammatory cytokine IL-10 (il10−/− mice), which develop spontaneously chronic colitis, have increased carcinogenesis with higher grade and invasiveness when being treated with AOM compared to wild type mice." (PMID 28632155, 2017). "In the IL-10-deficient mouse model (IL-10-/-), which is a valuable model to mimic conditions of human chronic colitis, monoassociation with E. faecalis induces severe intestinal inflammation." (PMID 26067254, 2015). "Further, two studies used a Rag IBD mice model (Rag mice lack functional T- and B-cells) where animals are reconstituted with IL-10−/− T-cells; IL-10 being a key immunoregulatory cytokine, IL-10−/−−deficient mice develop spontaneous chronic colitis." (PMID 25879741, 2015). "The impact of intestinal inflammation in overcoming colonization resistance was further supported by the finding that IL-10−/− mice suffering from chronic colitis were susceptible to C. jejuni infection." (PMID 22563475, 2012). "IL-10-deficient (IL-10−/−) mice develop chronic colitis, which is mediated by T-helper (Th)-1 cytokines." (PMID 22943587, 2012). "Mice with a deficiency in IL-10 spontaneously develop chronic colitis characterized by infiltration of lymphocytes, monocytes and neutrophils." (PMID 21060867, 2010). "Systemic and oral LMP-420 treatment for 16 days decreased colonic TNF levels in IL-10-deficient mice with chronic colitis, with a trend to decreased histologic inflammation for oral LMP-420." (PMID 18331642, 2008). "This study investigated the efficacy of LMP-420 as an anti-inflammatory agent in acute and chronic colitis induced by oral administration of dextran sulfate sodium (DSS) to mice and in chronic colitis following piroxicam administration to IL-10-deficient mice." (PMID 18331642, 2008). "IL-10-deficient mice (IL-10−/−) usually display chronic colitis in histology that is similar to humans with IBD and while the IL-10−/− mice treatment with Akk does not promote the development of short-term intestinal inflammation, long-term supplementation of Akk has not been completely evaluated." (PMID 36835309, 2023). "Although a previous study indicated potential for UCC118TM strain in an IL-10-deficient mouse model of chronic colitis, it has remained unclear until now whether Lactobacillus salivarius UCC118TM could be a good candidate for the treatment of IBD." (PMID 35889102, 2022). "Surprisingly, we found that neither Il33 expression, nor IL-33 producing fibroblasts were increased during the development of chronic colitis in Il10-deficient mice, although Il33 expression could be induced in Il10−/− mice by epithelial injury with DSS." (PMID 33953267, 2021).
Chronic colitis (continued). "Hence, C. coli infection of aged conventional IL-10-/- mice with chronic colitis was associated with pronounced systemic TNF-α secretion." (PMID 32664563, 2020). "Here, we tested whether transgenic expression of human IL-37 protects IL-10 deficient (IL-10KO) mice from chronic colitis." (PMID 31781119, 2019). "Most importantly, this EpaB-mediated defective adhesion of E. faecalis to the outer colonic mucus occurred exclusively in the susceptible milieu of inflamed IL-10-/- mice, where bacterial penetration of / adhesion to mucus is an important feature contributing to chronic colitis pathogenesis." (PMID 26067254, 2015). "Furthermore, it was demonstrated that mice deficient in IL-10 production developed chronic colitis." (PMID 40227443, 2025). "Furthermore, we could demonstrate that conventional mice suffering from chronic colitis due to IL-10 deficiency could be stably infected with C. jejuni at intermediate levels for two weeks." (PMID 22808254, 2012). "In this study, we found that 5-ASA or monotropein remarkably decreased serum levels of TNF-a and IL-6 cytokines and increased levels of anti-inflammatory cytokine IL-10 in chronic colitis mice." (PMID 40041493, 2025). "Evidence suggests that IL‐6 is a key cytokine in chronic colitis, and reduced IL‐10 activity leads to increased levels of IL‐6, IFN‐γ, and TNF." (PMID 40953838, 2025). "In this study, we investigated the protective effects of the culture supernatant of A.m-SN in IL-10−/− mice, a well-established model of spontaneous chronic colitis." (PMID 41333470, 2025). "Our previous study also showed that Clonorchis sinensis Molecular chaperones HscB (CsHscB) derived from C. sinensis can attenuate DSS-induced acute and chronic colitis by inducing a high level of IL-10." (PMID 40014218, 2025). "More recently, in an IL-10 knockout model of chronic colitis, reduced mucosal damage and prolapse rates were observed in response to Nrf2 activation." (PMID 38672464, 2024). "Compared to normal mice, the mRNA expression of TNF-α slightly increased while that of IL-10 significantly decreased in mice with chronic colitis." (PMID 38110964, 2023). "After treatment with various doses of PS-NPs, both rising TNF-α mRNA expression and declining IL-10 mRNA expression in mice with chronic colitis significantly aggravated, which was opposite to that of 5-ASA." (PMID 38110964, 2023). "Whereas transfer of purified CD4 + lymphocytes from IL-10−/− mice to immunodeficient RAG mice results in the development of chronic colitis, with the CD4 + population as the predominant culprit." (PMID 36869359, 2023). "The purpose of this study was to investigate the efficacy and potential mechanism of JPQCD in reducing piroxicam-induced chronic colitis in IL-10−/− mice." (PMID 35186102, 2022). "In contrast to OVA-induced enteritis, changes on histological levels were clearly detectable in IL-10−/− mice which develop a spontaneous form of chronic colitis due to the missing anti-inflammatory cytokine IL-10." (PMID 35163137, 2022). "We set out to evaluate the immune cell lineages most reliant on integrin α4β7 to enter the intestine during chronic inflammatory conditions, using the IL-10−/− murine model of chronic colitis." (PMID 34433904, 2022). "We observed an increased number of MC and higher expression of MC proteases in IL-10−/− mice which develop a spontaneous form of chronic colitis due to the missing anti-inflammatory cytokine IL-10." (PMID 35163137, 2022). "IL-10 deficient (IL-10−/−) mice, a typical experimental model of IBD, spontaneously develop chronic colitis mediated by Th1 and Th17 cell with many similarities to human CD." (PMID 34743749, 2021). "Psae infection has been associated with pro-inflammatory immune response in the colon in IL-10(–/–) mice with chronic colitis." (PMID 34287254, 2021). "To determine the role of endogenous IL-33 in chronic colitis, we bred Il10−/−/Il33−/− mice and compared them to littermate Il10−/−/Il33+/+ mice." (PMID 33953267, 2021).
Chronic colitis (continued). "Similar results were obtained in IL10 knockout (IL10−/−) mice, using a chronic colitis model, in which GDNPs 2 were able to prevent splenic enlargement and colon length reduction, by downregulating TNF-α and IL-1β gene expression." (PMID 34065193, 2021). "IL10 is an anti-inflammatory cytokine and IL10-/- mice develop chronic colitis with marked increase in pathological type-I helper T cell response in SPF but not in germ-free conditions." (PMID 33537028, 2020). "We next assessed both, large intestinal and systemic tumor necrosis factor-α (TNF-α) secretion in IL-10-/- mice with chronic colitis following C. coli infection." (PMID 32664563, 2020). "Some studies also found that triptolide can relieve the intestinal inflammation of the chronic colitis observed in IL-10−/− mice." (PMID 33240279, 2020). "For the first time, we here show that C. coli induces intestinal and systemic inflammatory responses in conventional aged IL-10-/- mice with pre-existing chronic colitis." (PMID 32664563, 2020). "IL-10 knock-out mice develop chronic colitis, which supports the view that IL-10 has an important role in immune regulation." (PMID 31999939, 2020). "We have recently also shown that THC attenuated chronic colitis in IL-10 knockout mice through MDSCs induction." (PMID 32612530, 2020). "In the IL10tm1Cgn mouse (IL-10−/−), which is a well-characterized model of human chronic colitis, monoassociation with E. faecalis induces severe intestinal inflammation, whereas wild type mice remain disease-free." (PMID 31281321, 2019). "We tested various models of chronic colitis in IL-10-/- and FVB mice (induced with piroxicam, EtOH, TNBS, or DSS) with different dosage regimens, using clinical and small animal ultrasound scanners." (PMID 31534535, 2019). "We next surveyed macroscopic (i.e. clinical) and microscopic (i.e. histopathological and immunohistochemical) sequelae in Psae infected IL-10−/− mice with chronic colitis." (PMID 29704005, 2018). "In the following we quantitatively assessed large intestinal immune cell responses upon Psae infection of IL-10−/− mice with chronic colitis applying in situ immunohistochemistry." (PMID 29704005, 2018). "Conventional IL-10−/− mice with chronic colitis and healthy WT control animals were perorally infected with 109 colony-forming units (CFU) of a clinical MDR Psae strain." (PMID 29704005, 2018). "Consistent with this, in this study, we found that IL-33 induces Bregs (CD19+CD25+) and IL-10-producing Bregs (CD19+IL-10+) in the MLN of mice with DSS-induced chronic colitis." (PMID 30539029, 2018). "Taken together, peroral MDR Psae infection exacerbates macroscopic and colonic apoptotic sequelae as well as intestinal and systemic pro-inflammatory cytokine responses in IL-10−/− mice with chronic colitis." (PMID 29704005, 2018). "In this present study, we identified the omega-3 FA receptor GPR120 as an anti-inflammatory mediator in the chronic colitis model of IL-10 KO mice." (PMID 28039475, 2017). "The IL-10 KO mice mostly suffer from anemia, growth retardation and chronic colitis under specific pathogen-free (SPF) conditions." (PMID 28039475, 2017). "We therefore perorally challenged conventionally colonized TLR4-deficient IL10−/− mice and IL10−/− counterparts displaying comparably severe chronic colitis with a clinical MDR PA strain." (PMID 29151895, 2017). "IL-10 KO Treg-of-B cells successfully suppressed responder T cell proliferation; moreover, IL-10 KO Treg-of-B cells were able to attenuate chronic colitis induced by the colitogenic T cells and suppress the Th1 and Th17 response." (PMID 27581189, 2016). "Since GelE is known as a bacterial virulence factor relevant for the colitogenic activity of E. faecalis and upregulated under conditions of chronic colitis in IL-10-/- mice, we analyzed how GelE activity is affected by epaB or lgt deficiency." (PMID 26067254, 2015).
Chronic colitis (continued). "For example, others have used an adoptive IL-10−/− CD4+ T cell transfer model of chronic colitis in which piroxicam is administered to induce acute colitis." (PMID 25247786, 2014). "In the chronic colitis model, treatment with interleukin-10 and anti-IL-1 protected against DSS-induced colonic macroscopical and microscopical inflammation." (PMID 27785242, 2013). "Antibiotic treatment right after weaning prevented IL-10−/− mice from development of chronic colitis which usually becomes overt between 3 to 6 months of age, depending on housing conditions and the specific gut microbiota composition." (PMID 22808254, 2012). "To address this question we infected 6-months-old IL-10−/− mice with chronic colitis harboring a conventional gut microbiota with C. jejuni ATCC 43431." (PMID 22563475, 2012). "We have also shown that antibody-mediated neutralization of the CXCR3 ligand CXCL10 inhibits chronic colitis in IL-10-/- mice." (PMID 21858153, 2011). "Intragastric administration of Lc. lactis genetically modified to secrete IL-10 in situ in the intestine was shown to be effective in healing and preventing chronic colitis in mice." (PMID 21991534, 2011). "The therapeutic efficacy of TLE diet was assessed using dextran sulfate sodium (DSS) exposed mice and IL-10−/−;NF-κBEGFP mice, representing an acute and spontaneous chronic colitis model respectively." (PMID 19234608, 2009). "We used a brief exposure to the non-steroidal anti-inflammatory drug piroxicam to uniformly trigger the development of chronic colitis in 6 – 7 wk IL-10-/- mice." (PMID 18331642, 2008). "Conversely, both 5-ASA and monotropein could substantially decrease the expression of TNF-α and IL-6 and increase the expression of IL-10 in mice with chronic colitis." (PMID 40041493, 2025). "Likewise, Gunasekera and colleagues have demonstrated the mechanistic relationship between IL-10 and IL-22, suggesting important insights into the pathogenesis of chronic colitis in IL-10−/− mice." (PMID 40830617, 2025). "It was reported that adipokine apelin could ameliorate chronic colitis in Il10−/− mice by promoting intestinal lymphatic function." (PMID 39623906, 2024). "In addition, in a study using a chronic colitis mice model, IL-10 suppressed the inflammasome/IL-1β pathway, reduced the pathogenicity of Th17 cells, and suppressed IL-17 production, leading to the mitigation of intestinal inflammation." (PMID 37894114, 2023). "Even though IL-10 deficiency in B cells aggravates the outcome of DSS-induced chronic colitis, it does not contribute to the development of tumorigenesis in CAC, which suggests the presence of other immunosuppressive mechanisms." (PMID 37849749, 2023). "Interestingly, in this study the IL-10 producing Bregs exert suppressive effects on Th1/Th17 cells in mouse chronic colitis and then differentiate into IgA+ plasma cells in response to TLR activation." (PMID 37849749, 2023). "Thus, in order to dissect the roles of αEβ7 and α4β7 during chronic colitis, we treated IL-10−/− mice with an antibody against the α4β7-specific ligand, MAdCAM-1 (MECA-367)." (PMID 34433904, 2022). "Similarly, SJMHE1 treatment upregulated the expression of interleukin-10 (IL-10) mRNA, downregulated the expression of IL-17 mRNA and modulated the Th cell balance in mice with chronic colitis." (PMID 34488863, 2021). "In the present study, significant increases in the production of IL-6, IL-12p70, IL-1β, TNF-α, IFN-γ, IL-21, and IL-17A and decreases in the production of IL-10 were observed in the chronic colitis group compared with the control group, and these changes were restored by NAM treatment." (PMID 33748287, 2021). "Hence, C. coli infection of aged conventional IL-10-/- mice with pre-existing chronic colitis resulted in both, macroscopic and microscopic inflammatory sequelae." (PMID 32664563, 2020).
Chronic colitis (continued). "It has recently been shown that C. jejuni colonize the intestinal tract of five to six months old IL-10−/− mice with murine intestinal microbiota suffering from chronic colitis; however, the clinical signs for severe human campylobacteriosis such as bloody diarrhea were missing." (PMID 32231139, 2020). "In support, human microbiota associated IL-10-/- mice without chronic colitis displayed more pronounced colonic apoptosis three weeks following peroral C. coli as compared to mock application." (PMID 32664563, 2020). "With progressive aging, IL-10-/- mice develop chronic colitis due to the antigenic stimuli derived from their commensal gut microbiota starting approximately by the age of 2 to 6 months depending on the housing conditions and the murine gut microbiota composition." (PMID 32664563, 2020). "Hence, C. coli infection of conventional IL-10-/- mice with chronic colitis resulted in distinct innate and adaptive immune responses in the colon." (PMID 32664563, 2020). "Bis‐2‐(5‐phenylacetamido‐1,2,4‐thiadiazol‐2‐yl) ethyl sulfide treatment significantly ameliorated chronic colitis in the IL‐10−/−, as manifested by decreased disease activity index, body weight change, histological inflammatory degree and inflammatory cytokine expression." (PMID 31211512, 2019). "Finally, we found that the impact of CEC is beneficial to the host in a chronic colitis IL10−/− mouse model." (PMID 31391483, 2019). "In the current study, we started with IL-10-/- models of chronic colitis induced with piroxicam." (PMID 31534535, 2019). "Hence, viable commensals originating from the intestinal microbiota translocated to extra-intestinal compartments of MDR Psae colonized IL-10−/− mice with chronic colitis only." (PMID 29704005, 2018). "Hence, MDR Psae colonization of IL-10−/− mice with chronic colitis is accompanied by increased intestinal pro-inflammatory cytokine responses." (PMID 29704005, 2018). "In accordance with above observation, our data demonstrated that the expression level of IL-10, the absolute number and percentage of CD4+CD25+ and CD4+IL-10+ Tregs in MLN of mice with DSS-induced chronic colitis, were strikingly higher in the IL-33 group than in PBS group." (PMID 30539029, 2018). "Furthermore, viable commensals originating from the intestinal microbiota translocated to extra-intestinal compartments such as liver, kidney and spleen of Psae-infected IL-10−/− mice with chronic colitis only." (PMID 29704005, 2018). "Hence, Psae infection accelerates both macroscopic (i.e. clinical) and microscopic (i.e. colonic apoptotic) sequelae in IL-10−/− mice suffering from chronic colitis." (PMID 29704005, 2018). "IL-10−/− mice develop a chronic colitis after 12–15 weeks that worsens in an age-dependent manner." (PMID 30315190, 2018). "In conclusion, we here show that peroral MDR Psae challenge results in intestinal infection that exacerbates chronic colitis as indicated by macroscopic and colonic apoptotic sequelae as well as intestinal and systemic pro-inflammatory cytokine responses in IL-10−/− mice." (PMID 29704005, 2018). "Both cultural and culture-independent (i.e. molecular 16S rRNA based) analyses of fecal samples revealed that IL-10−/− mice with chronic colitis harbored comparable intestinal loads of the main intestinal bacterial groups before and 42 days after Psae challenge." (PMID 29704005, 2018). "The impact of IL-10 on Th17 cell function is also illustrated in a chronic colitis model." (PMID 27308096, 2016). "Various studies show that myeloid cell-specific STAT3 deficiency results in enhanced inflammation and chronic colitis as a consequence of a decrease in PMN-MDSCs and linked herewith a decrease in suppressive cytokines (e.g. IL-10), an increase in pro-inflammatory cytokines (e.g. IFN-γ) and iNOS." (PMID 27029037, 2016).